NAXD (NAD(P)HX dehydratase)
Description:
Catalyzes the dehydration of the S-form of NAD(P)HX at the expense of ATP, which is converted to ADP. Together with NAD(P)HX epimerase, which catalyzes the epimerization of the S- and R-forms, the enzyme allows the repair of both epimers of NAD(P)HX, a damaged form of NAD(P)H that is a result of enzymatic or heat-dependent hydration.
Synonyms: CARKD; LP3298; FLJ10769; PEBEL2
Tractability: PROTAC: ubiquitination databases record sites on it.
Gene: Protein-coding gene on chromosome 13 (110,615,512 to 110,639,996, forward strand). Ensembl gene ENSG00000213995.
Subcellular location: Mitochondrion
Pathways (Reactome):
Metabolism: Nicotinate metabolism
Gene Ontology:
Molecular function: ATP-dependent NAD(P)H-hydrate dehydratase activity; protein binding; hydro-lyase activity
Biological process: metabolite repair; nicotinate metabolic process; nicotinamide nucleotide metabolic process
Cellular component: mitochondrion; mitochondrial matrix
Genetic constraint (gnomAD): Loss-of-function variants: 17 observed, 30.26 expected, observed/expected ratio (o/e) 0.56, 90% interval 0.38 to 0.84. The upper end of that interval is the gene's LOEUF score, 0.84, which puts it in group 3 of 6, group 1 being the genes least tolerant of losing a copy. Missense variants: 403 observed, 422.09 expected, observed/expected ratio (o/e) 0.95, 90% interval 0.88 to 1.04. Synonymous variants: 180 observed, 171.59 expected, observed/expected ratio (o/e) 1.05, 90% interval 0.93 to 1.19.
Gene-disease validity (ClinGen):
ClinGen rates the evidence that NAXD causes each of these diseases.
mitochondrial disease (autosomal recessive): Definitive.
Homologues: Orthologues: chimpanzee NAXD (83% identical), macaque NAXD (82% identical), mouse Naxd (80% identical), dog NAXD (80% identical), rat Naxd (80% identical), guinea pig NAXD (74% identical), tropical clawed frog naxd (72% identical), rabbit NAXD (68% identical), zebrafish naxd (64% identical), pig NAXD (62% identical), Drosophila melanogaster Naxd (42% identical), Caenorhabditis elegans R107.2 (39% identical).
Diseases named in the same sentence as NAXD in open-access papers:
NAXD is named in the same sentence as 6 diseases in open-access papers, as found by Europe PMC text mining. Sharing a sentence is not in itself a finding about the gene and the disease. The quoted sentences say what the papers report.
breast carcinoma (2 papers, 2024 to 2025). "Of the two dbVar whole-gene DUPs, the COL4A2 339,611 bp CG, with breakpoints disrupting COL4A1 and NAXD, observed in a single African patient is defined as a PP-SV, as COL4A2 indicating oncogenic behaviour in gastric and breast cancers." (PMID 38947031, 2024).
cancer (2 papers, 2021 to 2025). A tumor composed of atypical neoplastic, often pleomorphic cells that invade other tissues. "The present study deepens our knowledge of the importance of the NAXD-mediated repair mechanisms of NADHX in NAD+ metabolism and highlights the necessity to further investigate the possible involvement of NADHX in various NAD+-associated diseases such as cancer, ageing and metabolic diseases." (PMID 40113573, 2025). "Of the coexpressed genes, NAXD and BIVM also displayed hazard ratios comparable to that of ERCC5 in LGG, although their association with cancer has not been reported." (PMID 34966786, 2021).
NAXD also shares sentences with these, for which no sentence is quoted: brain edema (1 paper); metabolic disease (1); Mitochondrial myopathy (1); myopathy (1).